KIF3A (kinesin family member 3A)
Diseases named in the same sentence as KIF3A in open-access papers (continued):
Sharing a sentence is not in itself a finding about the gene and the disease.
KIF3A also shares sentences with these, for which no sentence is quoted: mastitis (2 papers); Osteopenia (2); allergic rhinitis (1); Alström syndrome (1); cleft palate (1); conjunctivitis (1); demyelinating disease (1); dyslexia (1); esophageal cancer (1); holoprosencephaly (1); hyperglycaemia (1); insulinoma (1); lipomatosis (1); neurodegenerative disease (1); ovarian carcinoma (1); primary ciliary dyskinesia (1); psoriatic arthritis (1); renal carcinoma (1); renal failure (1); Retinal dystrophy (1); sarcopenia (1); schizophrenia (1); small cell lung carcinoma (1); systemic lupus erythematosus (1); Virus infection (1).